STK11 (serine/threonine kinase 11)
Diseases named in the same sentence as STK11 in open-access papers (continued):
Sharing a sentence is not in itself a finding about the gene and the disease.
tumor (continued). "We plan to use single-cell techniques to identify the interactions between the tumor cells and the immune cells of the microenvironments to demonstrate how a tumor-intrinsic loss of function mutation in STK11/LKB1 drives an immune response conducive to host wasting." (PMID 37092555, 2023). "Therefore, STK11 mutation is supposed to be the crucial driver of cancer progression and resistance to tumor therapy." (PMID 37506141, 2023). "Use of the presence of a tumor STK11/LKB1 mutation will also permit cachexia trials to enrich for patients who may most benefit from a therapeutic intervention." (PMID 37092555, 2023). "KEAP1 and STK11 mutations are associated with positive survival impact in KRAS-WT tumours." (PMID 36864508, 2023). "Thus, genomic aberrations in STK11/LKB1 have been reported to mediate a less-immunogenic-tumor microenvironment and be a major cause of resistance to anti-PD-1 antibody treatment in NSCLC patients." (PMID 36672698, 2023). "Consistent with this hypothesis, RMC-6272 40 induces widespread apoptosis and deep tumor regressions in a xenograftmodel of KRASG12C mutantNSCLC bearing a loss of function mutation in STK11, a negative regulator of mTORC1." (PMID 36533617, 2023). "In addition, STK11 mutations are associated with a reduced density of tumor-infiltrating cytotoxic CD8+ T lymphocytes and an increase in pro-inflammatory cytokine production, leading to a more immunosuppressive tumor microenvironment." (PMID 37373999, 2023). "We expect that even for early-stage disease, the presence of an STK11/LKB1 tumor variant should galvanize the patient’s multidisciplinary team to emphasize supportive care measures focused on nutrition, quality of life, and other metrics before significant wasting manifests." (PMID 37092555, 2023). "Evaluation of tumor STK11/LKB1 loss of function in promoting human NSCLC-associated cachexia." (PMID 37092555, 2023). "To explore whether tumors developed in Stk11ec−/− mice originated from Stk11 deleted ECs, we performed immunochemical staining of Lkb1 (encoded by Stk11) in tumor sections from Stk11ec−/− mice." (PMID 35115536, 2022). "In CodeBreak100 (phase II), among 104 patients whose tumours could be analyzed for co-mutations in STK11 and KEAP1, the ORR to sotorasib was 39%." (PMID 36284306, 2022). "STK11 mutations are often associated with an “immune-cold” tumor microenvironment with low PD-L1 and T-cell densities, high granulocyte colony-stimulating factor and IL-8 family cytokines, and production of neutrophil-like cells and myeloid cell-recruiting chemokines such as IL-6." (PMID 36430528, 2022). "UPN3155 acquired an STK11 mutation (a tumour suppressor) after disease progression." (PMID 36380727, 2022). "Comparing somatic mutation rates in SMGs between clusters using binomial regression identified PIK3CA (FDR = 0.001) and EP300 (FDR = 0.046) mutations as disproportionally more common in C1 tumours and STK11 (FDR = 0.005) and NF2 (FDR = 0.045) as enriched in C2 tumours." (PMID 36207323, 2022). "As the poor prognosis is recognized in SMARCA4-deficient tumors, the presence of frequent co-mutation with other tumor suppressor genes, such as STK11 and/or KEAP1, further dampens the regrettable overall survival and shortens the progression free survival outcome of the disease." (PMID 34440689, 2021). "Similarly, SNVs in the gene STK11 (serine/threonine kinase 11), encoding a kinase with tumour suppressor function, were found to promote leukemic progression in patients with MPN." (PMID 34068690, 2021). "The increased tumor volume in the Stk11 deficient tumors also led to decreased survival." (PMID 33652656, 2021). "STK11 mutations are present in many different tumor types but with varying frequencies." (PMID 33572782, 2021).
tumor (continued). "Genetic ablation of STK11 in a KRAS-driven murine model of NSCLC demonstrated an accumulation of neutrophils with T-cell suppressive capacities associated with a decreased number of tumor-infiltrating lymphocytes and a reduced expression of PD-L1 in tumors." (PMID 34831355, 2021). "STK11 mutations in tumor cells also have tumor-extrinsic functions." (PMID 34831355, 2021). "It is postulated that mutations in STK-11 gene encoding for the serine/threonine kinase family that acts as a tumor suppressor may underlie susceptibility to IH-induced metabolic dysfunction, as illustrated by CRL-1424 cells." (PMID 34638272, 2021). "STK11 mutations cause LKB1 protein truncation and loss of tumour suppressive function." (PMID 34203378, 2021). "Recently, there is increasing evidence that loss of STK11/LKB1 may be involved in the modulation of the tumor immune microenvironment." (PMID 34831355, 2021). "The presence of co-mutations such as STK11 or KEAP1 shape the tumor immune microenvironment and might has an impact on treatment efficacy." (PMID 35096591, 2021). "In addition, STK11/LKB1 inactivated mutations were related with reduced expression of PD-1 ligand PD-L1 in tumor cells." (PMID 32206449, 2020). "Co-mutation of STK11 was shown to cause the accrual of neutrophils with T-cell-suppressive effects, accompanied with an analogous elevation in the production of T-cell depletion biosignatures and tumor-promoting cytokines." (PMID 33194652, 2020). "Nonetheless, the methylation status of the STK11 promoter region may be associated with a decrease in expression levels observed in tumor samples; it would be necessary to analyze the entire region that covers 2500 pb." (PMID 32911741, 2020). "Loss of STK11 would lead to cell polarity disorganization and induce tumor growth." (PMID 32206449, 2020). "For example, tumor IGC-10-1179 had STK11 mutated in the trunk and deleted in a branch." (PMID 32424208, 2020). "Another interesting prognostic biomarker may be represented by STK11 (serine/threonine kinase 11), one of the most mutated tumor-suppressor genes in NSCLC, that seems to be frequently associated with KRAS mutations." (PMID 31590386, 2019). "In murine models, inactivation of the tumor suppressor gene STK11/LKB1 led to significant increases in tumor-promoting cytokines and neutrophil activity; treatment of mice with an IL-6 antibody decreased the degree of tumor-associated neutrophils and improved survival as compared to control mice." (PMID 29619344, 2018). "Although STK11 is inactivated by a large spectrum of truncating mutation and behave as a tumor suppressor gene in different tumor models through mTOR inhibition, recent studies suggest that STK11 may also gain oncogenic properties." (PMID 26625312, 2017). "Interestingly, mTOR related gene sets had similar expression levels in STK11ex1-2 and STK11ex3-9, confirming that both types of tumor share the loss of STK11 tumor suppressor activity and subsequent activation of the mTOR pathway." (PMID 26625312, 2017). "Other studies have shown that STK11 is associated with tumor metastasis and more aggressive tumors." (PMID 25541970, 2014). "However, four of the six patients with STK11 mutations succumbed within 24 months following surgery and the tumor recurred in one of the two surviving patients." (PMID 24179492, 2013). "Hence, we believe that the nomenclature of Peutz‐Jeghers‐associated TSCSTs could be modified to include invasive tumours with STK11 alterations (e.g., ‘large cell hyalinising Sertoli cell neoplasia/tumour’)." (PMID 41384702, 2026).
tumor (continued). "Furthermore, oncogenic KRAS might exacerbate oxidative stress and anabolic metabolism, potentially synergizing with KEAP1/STK11 co-mutations to drive tumor aggressiveness." (PMID 41541668, 2026). "The germine STK11 gene mutation was found, which may play an important role in tumor development." (PMID 40018404, 2025). "The STK11/LKB1 mutation may play an important role in tumor development." (PMID 40018404, 2025). "Furthermore, among the three KC subtypes, STK11 mutations were predominantly observed in KC1 tumours, suggesting that KC1 may exhibit resistance to both G12Ci and immunotherapy." (PMID 41025426, 2025). "So the deficiency of STK11 may lead to spontaneous tumor formation." (PMID 40696413, 2025). "In addition, STK11 mutation is associated with tumor therapy resistance." (PMID 37506141, 2023). "Previous studies have also suggested that some genetic alterations in the tumor cells, such as somatic mutations in serine/threonine kinase 11 (STK11) or in kelch-like ECH-associated protein 1 (KEAP1), could serve as biomarkers to predict responses to ICIs in NSCLC." (PMID 36835030, 2023). "In contrast, the inactivation of Stk11 is associated with an immunosuppressive microenvironment and leads to the accumulation of neutrophils with T cell-suppressive effects, an increase in T-cell exhaustion markers and the secretion of tumor-promoting cytokines." (PMID 35406531, 2022). "Based on a previously published work, the Authors speculated that the concomitant loss of STK11 together with mutations in an oncogenic pathway (KRAS/RAF) promotes IL-6 secretion by tumor cells, which, in turn, can determine the recruitment of neutrophils in the tumor microenvironment." (PMID 33168050, 2020). "Consistently, immune infiltration analysis revealed striking reductions in various immune cells in KEAP1-, STK11- or CDKN2A-mutated tumors, characterizing the suppressive tumor immune microenvironment (TIME)." (PMID 41491583, 2026). "STK11 mutations frequently co-occur with KRAS and KEAP1 alterations, exhibit low PD-L1 expression, an immunosuppressive tumor microenvironment that leads to the development of PD-1/PD-L1 resistance." (PMID 42187558, 2026). "WES/WGS and RNA-seq confirmed the poor prognostic effect of KEAP1, STK11, and CDKN2A mutations, which were characterized by the suppressive tumor microenvironment and attenuated humoral immunity." (PMID 41491583, 2026). "The poor prognostic value of KEAP1, STK11, and CDKN2A mutations was further validated in the tumor tissue WES/WGS data." (PMID 41491583, 2026). "Taken together, baseline KEAP1, STK11, and CDKN2A mutations detected by liquid biopsy indicate a poor prognosis, which was also confirmed by tumor tissue-based mutation sequencing data." (PMID 41491583, 2026). "Given that both migration and proliferation are enhanced with the loss of LKB1 activity combined with the prevalence of STK11 genetic alterations in cancer biopsies, LKB1 was marked as a tumor suppressor." (PMID 39735555, 2025). "The loss of STK11 function is the well-known cause for the activation of the AMPK/mTOR pathway, which, paradoxically, enables tumor cells to survive and become resistant to metabolic stress." (PMID 41155343, 2025). "PY8119 parental and Stk11-KO cells were injected into the mammary fat pads, and Stk11-KO tumors developed significantly larger tumor volumes than those derived from parental cells." (PMID 41051525, 2025).
tumor (continued). "Results were validated against biochemical properties, alternative functional assays (including STK11 essentiality in HAP1 cells and enrichment in mouse-xenografted A549 tumours), known pathogenic and benign variants, and clinical phenotypes." (PMID 40791513, 2025). "An additional tumour suppressor gene frequently mutated in NSCLC is STK11, which encodes the liver kinase B1 (LKB1) protein, a master kinase that regulates cell polarity, metabolism, proliferation and migration." (PMID 40849356, 2025). "Most mice show ADC pathology, and the incidence of AST and tumor burden are also greatly decreased, highlighting LSD1 as a potential therapeutic target for STK11-mutated ASLC." (PMID 40568576, 2025). "It has been reported that KEAP1 and STK11 variants are associated with poorer responses to ICI, especially with lower PD-L1 scores of the tumor." (PMID 40869405, 2025). "Survival benefits were observed across PD-L1 strata, tumor histologies, and high-risk molecular subgroups such as KRAS, STK11, and KEAP1, and in patients with brain metastases." (PMID 41479494, 2025). "In breast cancer, STK11 signaling influences the tumor immune microenvironment through interactions with tumor-infiltrating immune cells." (PMID 40860288, 2025). "Tumor cells evade immune recognition through antigen presentation defects (e.g., HLA-I loss), oncogenic pathway activation (e.g., STK11/LKB1 mutations driving metabolic reprogramming), and epigenetic silencing of tumor antigens." (PMID 41267030, 2025). "In addition, loss of STK11 function has been demonstrated to promote robust immune escape in murine lung tumor models through the recruitment of CD11b+Gr-1+TANs and a concomitant reduction in T cell infiltration, thereby fostering an tumor immunosuppressive microenvironment." (PMID 41254689, 2025). "Currently, the diagnosis of an STK11 adnexal tumor requires molecular confirmation of STK11 inactivation/alterations." (PMID 40739655, 2025). "The STK11 gene encodes for liver kinase B1 (LKB1), which is a tumour suppressor that activates AMP-activated protein kinase (AMPK)." (PMID 40647497, 2025). "Third, we tested the function of STK11 variants by introducing variant-expressing A549 as mouse xenografts, in which expression of wild-type STK11 restricted growth of xenografted tumor cells." (PMID 40791513, 2025). "Recently, it has been proved that MET combined with PD-1 inhibitor enhanced anti-tumor efficacy in STK11 mutant NSCLC through inhibition of STING ubiquitination, suggesting a positive pro-immune effect of MET in patients with poor response to immunotherapy." (PMID 40221409, 2025). "Given previous reports linking KEAP1/STK11 co-mutations to an immune cold phenotype in LUAD, we sought to explore the relationship between KYNU expression and tumor immune infiltration." (PMID 40427178, 2025). "STK11 (serine/threonine kinase 11; LKB1) is a tumor suppressor; its loss in NSCLC disrupts AMPK signaling, rewires metabolism, and correlates with poor response to immunotherapy." (PMID 41154602, 2025). "STK11, also known as LKB1 (Liver kinase B1), whose loss-function mutation occurs in approximately 10% of NSCLC, is a tumor suppressor gene that plays a critical role in cellular processes such as metabolic reprogramming, cell polarity, and proliferation." (PMID 41378285, 2025). "CDKN2A/B co‐mutations were significantly represented in tumours with STK11 (63%, 10/16, p = 0.024), KEAP1 (59%, 10/17, p = 0.045), and SPEN (90%, 9/10, p < 0.001) alterations, and in all tumours with MTAP alterations (100%, 16/16, p < 0.001)." (PMID 41015991, 2025). "On the other hand, STK11 and KEAP1 mutations are strongly associated with an immunosuppressive tumor microenvironment." (PMID 40427178, 2025). "Positive DLL3 expression (≥1% tumor cells) correlated with STK11/KEAP1 mutations (characteristic of NSCLC-like LCNEC, as STK11/LKB1 mutations are frequent in NSCLC)." (PMID 41200177, 2025).
tumor (continued). "STING activation has been shown to restore tumour immunogenicity and T cell priming in STK11-mutant tumours." (PMID 40647497, 2025). "This mutation is often accompanied by other genetic alterations, such as those in the STK11 gene, which can further influence the tumor’s behavior and response to treatment." (PMID 40575565, 2025). "This suggests that, beyond the well-known STK11/KEAP1, alterations in other tumor suppressors like SMARCA4 (which often co-mutates with KRAS in smokers) and cell cycle regulators (CDKN2A loss) can also diminish the efficacy of KRAS inhibitors." (PMID 40723270, 2025). "Only CD11b+Ly6C−Ly6G+ PMN-MDSCs among tumor-infiltrating immune cells were increased in Stk11-KO tumors with an adjusted P value = 0.082." (PMID 41051525, 2025). "This study provides the first direct evidence of tumor progression from PTC to SCC, likely created by sequential loss‐of‐function of tumor suppressor genes (KEAP1 and STK11), in humans." (PMID 40600748, 2025). "We excluded another case of putative SCLEC from our study because it showed morphological and immunophenotypical features suggestive for STK11 adnexal tumor on pathological review; molecular analysis confirmed the presence of STK11 alteration in that case." (PMID 38418687, 2025). "Inhibition is controlled by the phosphorylation of ACC, a process influenced by the STK11/LKB1 tumor suppressor pathway." (PMID 40487761, 2025). "For example, tumors containing a KRAS/STK11 co-mutation primarily possess a tumor microenvironment (TME) along with limited immune responses, missing the CD8+ tumor-infiltrating lymphocytes that comprise many T regulator cells." (PMID 40075634, 2025). "Co‐occurring alterations with KRAS included FLT1 (28%, 9/32, p = 0.033), APC (16%, 5/32, p = 0.015), and KEAP1 (16%, 5/32), with four of these tumours also harbouring STK11 alterations, forming a KRAS‐KEAP1‐STK11 mutational profile (13%, 4/32)." (PMID 41015991, 2025). "Another key genetic alteration is the loss of STK11, which encodes liver kinase B1 (LKB1), the second most frequently mutated tumor suppressor in NSCLC (17–23% of cases)." (PMID 40725389, 2025). "As is the case with the presented patient, tumor findings of mutant KRAS and the loss of STK11 confer a poor prognosis." (PMID 41257133, 2025). "Inactivating aberrations in STK11 have been identified as critical drivers of an immunosuppressive tumor microenvironment in NSCLC, characterized by diminished infiltration of CD3+, CD4+, and CD8+ tumor-infiltrating lymphocytes and an accumulation of TANs." (PMID 41254689, 2025). "STK11 mutations often co-occur with activating KRAS mutations and are associated with aggressive tumor behavior, immunosuppressed phenotypes, and reduced response to therapy." (PMID 40725389, 2025). "It results from a germline mutation on chromosome 19p13.3 in the serine/threonine kinase 11 (STK11/LKB1) tumour suppressor gene." (PMID 40062058, 2025). "CXCL1, a chemokine well documented for its role in regulating tumor-infiltrating immune cells, was found to be upregulated after suppression of STK11." (PMID 41051525, 2025). "To further investigate the role of PEBP1 and STK11 co-expression within the tumor microenvironment (TME), we conducted a comprehensive set of analyses." (PMID 40806276, 2025).